CCL2 (C-C motif chemokine ligand 2)
Diseases named in the same sentence as CCL2 in open-access papers (continued):
Sharing a sentence is not in itself a finding about the gene and the disease.
tumor (continued). "CCL2 first recruited tumor cells to hydrogels, and then EVs loading GM‐CSF mRNA and Ce6 were swallowed by these tumor cells, resulting in tumor cells killed by sonodynamic therapy while DCs were stimulated to mature state by the GM‐CSF coordinating with dead tumor cells for further antitumor effect." (PMID 41476648, 2025). "Furthermore, CCL2 secreted by tumor cells as well as IL-8 secreted by CAFs induces macrophage recruitment." (PMID 40165895, 2025). "CCL2 is high in both serum and tumor tissue from patients with non-small-cell lung cancer." (PMID 40076892, 2025). "Additionally, tumor cells can secrete various cytokines and chemokines, such as CCL2 and CSF-1, which promote the migration of monocytes to the tumor site and facilitate their polarization into different types of TAM." (PMID 40370720, 2025). "In the future, a deeper investigation into the role of CCL2 in the tumor microenvironment may hold promise for developing strategies to overcome drug resistance." (PMID 41276817, 2025). "Moreover, key cytokines and chemokines, including IL-6, IL-10, IL-8, TNF-α, TGF-β, and CCL2/5, demonstrate subtype-specific and context-dependent effects, acting as both tumor-promoting and tumor-suppressing agents through complex signaling networks." (PMID 40909271, 2025). "Beyond the association of SPACA6-hosted miRNA cluster with tumor progression, we detected a positive correlation between SPACA6, miR-99b, miR-125a and let-7e with key immunosuppressive factors such as TGFβ and CCL2, suggesting a potential role in sustaining an immunosuppressive TME." (PMID 41550951, 2025). "Given the high expression of CCR2 and migration-related genes in NOD2-dependent LY6Clo I-NCMs, we hypothesized that signaling through CCL2/CCR2 plays a role in I-NCM–induced tumor regression." (PMID 39545417, 2024). "Moreover, blocking the CCL2/CCR2 pathway prevents the recruitment and infiltration of inflammatory monocytes and the M2 polarization of tumor-associated macrophages (TAMs)." (PMID 39199602, 2024). "Furthermore, a wealth of clinicopathological information supports the correlation between elevated tumor CCl2 concentrations and heightened TAM infiltration as well as metastases." (PMID 38655133, 2024). "Additionally, treatment of tumor cells with an astrocyte-conditioned medium or the chemokine CCL2 resulted in upregulation of MUC5AC expression and enhanced brain colonization." (PMID 38825648, 2024). "Tumor cells promote the migration of myeloid-derived suppressor cells (MDSCs) and macrophages into the tumor microenvironment by secreting chemokines such as CCL2, CCL5, and CXCL12." (PMID 39717759, 2024). "PDGF-BB plays a role in tumor stroma development by inducing CCL2-dependent macrophage recruitment." (PMID 38543085, 2024). "Furthermore, the combination of CCR2 (the receptor for CCL2) inhibition and anti-PD-1 therapy has been shown to enhance tumor responses over anti-PD-1 monotherapy through enhanced recruitment and activation of CD8+ T-cells." (PMID 38575562, 2024). "While the CCR2/CCL2 axis may recruit myeloid cells that are hijacked by the tumour to become immunosuppressive, these cells can promote an anti‐tumour response when activated to a pro‐inflammatory state." (PMID 38426634, 2024). "Following the release from the bone marrow, monocytes enter the circulation and are subsequently recruited in the TME by various chemokines (such as M-CSF, CCL2, CCL5, CXCL12, and VEGF) secreted by tumor cells, and then differentiate into tumor associated macrophages (TAMs)." (PMID 39606239, 2024). "However, an increasing number of recent studies strongly suggest that CCL2 acts as a tumor-promoting factor." (PMID 38769475, 2024). "Interestingly, CCL2, IL-6, and IL-8 production by CAFs were significantly higher when the cells were co-cultured with both macrophages and tumor cells, pointing towards intricate crosstalk required for CAF signaling." (PMID 38455762, 2024).
tumor (continued). "Moreover, miR‐210‐3p inhibitor‐treated A549 tumor spheroids significantly altered the mir‐210‐3p and CCL2 mRNA levels, reducing spheroid dimensions, and enhancing the monocyte population within the spheroids." (PMID 35658112, 2024). "Additionally, the co-culture of ASCs with melanoma cells upregulates the expression of CXCL12/13 and CCL2, further promoting the recruitment of ASCs to the tumor microenvironment." (PMID 39519109, 2024). "In most cancers, tumor hypoxia downregulates the expression of C‐C motif chemokine 2 (CCL2), and this downregulation has been implicated in monocyte infiltration and tumor progression; however, the molecular mechanism is not yet clear." (PMID 35658112, 2024). "By analyzing the differentially expressed genes between the cryoablation group and the control group, we found that cryoablation of the primary tumor significantly increases the expression levels of several chemokines in the secondary tumors, including Ccl2, Ccl6, and Ccl7." (PMID 39489086, 2024). "Furthermore, in vivo CCL2 expression in muscle was negatively associated with myofiber size and alterations in MYH and MYL expression in the CCL2 delivery and 4T1 tumor models." (PMID 38973385, 2024). "Additionally, macrophages recruited by CCL2 primarily promote tumor invasion and spread in the lungs." (PMID 38787372, 2024). "It has been reported that vascular ECs undergoing inflammatory changes in the tumor microenvironment secrete high levels of CCL2, which attracts neutrophils and activates them, suggesting that neutrophil activation takes place through the inflamed ECs as a new mechanism." (PMID 38098255, 2024). "Similarly, the HIF‐1A inhibitor (PX‐478)‐treated A549 tumor spheroids remarkably altered the mir‐210‐3p and CCL2 gene expressions in hypoxic conditions." (PMID 35658112, 2024). "In addition to enhancing the trafficking of anti-fibrotic monocytes, CCL2 has also recently been demonstrated as being critical to orchestrating NK-cell-mediated anti-tumor effects in PDAC models." (PMID 38339310, 2024). "Il1α, Ccl2, Cxcl5, and Cxcl10 were significantly downregulated in Ifi35ko 4T1 tumor cells." (PMID 38216673, 2024). "It reported that inhibition of CCL2/CCR2 axis could reduce tumor infiltration and stimulate T cell responses." (PMID 39707188, 2024). "However, the STING inhibitor (C-176, H151) can alleviate the ER stress response and reduce the secretion level of CCL2 in tumor cells with high chromosomal instability." (PMID 39280014, 2024). "Also, a marked reduction of CCL2 expression along with the induction of mir‐210‐3p gene expression was observed in hypoxic tumor spheroids as compared to the normoxic state." (PMID 35658112, 2024). "In addition, studies on mouse ovarian cancer models have shown that the anti-tumor effects of anti-CCL2 antibody therapy can be enhanced by combining it with chemotherapy or immunotherapy." (PMID 39403370, 2024). "This may be due to the fact that CCL2 mainly acts through chemotactic attraction, and under its stimulation, tumor cells tend to enhance their invasion and migration ability rather than metastasis ability." (PMID 38221626, 2024). "On the other hand, once these CCR2-positive immune cells are within the tumor microenvironment, they might contribute to tumor growth, metastasis, and immune evasion through their interaction with CCL2." (PMID 38755605, 2024). "In carcinogenesis including AML, CCL2 acts oncogenic by organizing the tumor microenvironment." (PMID 39689089, 2024). "Regarding the pro-tumorigenic role, studies have shown that the expression of chemokines such as CCL2 and CCL3 can recruit tumor-associated macrophages (TAMs) of the M2 subtype to the tumor microenvironment (TME), thereby enhancing the progression of ductal carcinoma in breast tissue." (PMID 39769501, 2024).
tumor (continued). "Studies showed that activation of YAP is an important step in TAM recruitment towards TME in HCC via modulating the levels of IL-6, CSF-1 and CCL-2 secreted by the tumour cells, thereby inducing the formation of tumour initiation cells and remodelling the composition of TME." (PMID 39320855, 2024). "Tumor stromal cells can also induce infiltration of MDSCs by secreting CCL2 and CXCL12." (PMID 38397901, 2024). "Additionally, this study used IHC to detect CCL2 expression within TLS regions and surrounding tumor tissue, revealing a higher proportion of CCL2 positivity in the TLS regions, suggesting a possible association between CCL2 and TLS formation." (PMID 39595209, 2024). "Also, Ccl2, Ccl7, and IL-15 which have anti-tumor responses were upregulated in this cluster, which likely contributes to the IFNα-mediated antiphagocytic activity of macrophages." (PMID 39559365, 2024). "To investigate whether CCL2 promotes a metastatic phenomenon of tumour cells, we evaluated the invasion of lung tumour cells using a microfluidic chip assay." (PMID 37850256, 2024). "RT combined with CAR-T cells can stimulate the production of chemokines by immune cells (such as macrophages and dendritic cells), endothelial cells, and even the tumor cells themselves, including C-C motif chemokine ligand 2 (CCL2) and C-X-C motif ligand 9 (CXCL9)." (PMID 39578426, 2024). "However, it can be assumed that CCL2 originates from immune cells, tumor cells, and endothelial progenitor cells." (PMID 39199602, 2024). "Macrophages could be polarized to the tumor growth-promoting M2 subtype in the tumor environment by cytokines, such as CCL2, CCL5, CCL18, and TGFB1 and the mRNA levels of the transcription factor IRF4." (PMID 39272860, 2024). "Senescent tumor cells are also able to summon NK cells via CCL2." (PMID 39766202, 2024). "CCL2 is released by tumor cells, stromal cells, and monocytes in TME." (PMID 39065562, 2024). "Studies on CRISPR Cas9-mediated EZH2 knockdown in breast cancer cell lines MDA-MB-231, MCF7, and BT549, reported DNA demethylation and consequent upregulation of miR-124-3p and inhibition of its target gene CCL2, which helps recruit macrophages to the tumor site." (PMID 39660126, 2024). "Thus, this suggests that CCL2 is critical for NK cell accumulation and anti-tumor responses in a murine KPC PDAC model." (PMID 38339310, 2024). "Furthermore, RT-induced CCL2 production has been linked to the migration of MDSC to MC38 mouse colorectal cancers, resulting in T cell suppression and compromised tumour responses to HDRT." (PMID 38833685, 2024). "Notably, our computational analysis of this high-dimensional data suggests that the key changes correlating with inhibition of tumor growth include the downregulation of CCL-2, CCL-7, CCL-12, and the upregulation of CXCL-10, CCL-24, CXCL-12 and IL-3." (PMID 38575562, 2024). "Furthermore, it has been demonstrated that CCL2 derived from MCs facilitates the migration of endothelial cells in SM, both in vitro and in vivo, thereby modifying the tumor microenvironment to favor fibrosis and angiogenesis." (PMID 39850880, 2024). "CCL2 can additionally be expressed by CAFs in later stages of tumor growth and formation." (PMID 38339310, 2024). "The recruitment of TAMs to the tumoral area is dependent on immunomodulation exerted by tumor cells, which is mostly dependent on the chemokine (C-C motif) ligand 2 (CCL2), vascular endothelial growth factor (VEGF), platelet-derived growth factor (PDGF), and CSF-1." (PMID 39457693, 2024). "Additionally, C-C motif chemokine ligand 2 (CCL2) facilitates the uptake of tumor exosomes by immune cells, which ultimately leads to the enrichment of myeloid suppressive cells at future metastatic sites." (PMID 38543914, 2024).
tumor (continued). "Additionally, they observed that NT157 not only reduced tumor burden but also suppressed the expression of various pro-tumorigenic chemokines (e.g. CCL2) and cytokines (e.g. IFN-γ and IL-1β), which are critical for TAM recruitment." (PMID 38229160, 2024). "Intriguingly, Ccr2 and Ccl2, two proteins that are preferentially expressed in tumor cells and are critical for cancer cell proliferation, were strongly downregulated, suggesting a potential mechanism through which I-BRD9 inhibits AML but not HEK293T cell growth." (PMID 38126767, 2024). "In addition, NF-κB/CCL2 signaling pathway plays a key role in tumor progression, invasion and metastasis in a wide range of human cancers." (PMID 38397187, 2024). "Beyond immune modulation, CCL2 directly influences tumour angiogenesis and cellular dynamics." (PMID 39706820, 2024). "Research has extensively shown that astrocytes have the ability to control the attraction of tumor-associated macrophages (TAMs) to the tumor microenvironment (TME) through CCL2, leading to the progression of glioblastoma by encouraging a pro-tumor phenotype in TAMs." (PMID 39403379, 2024). "Notably, treatment-induced tumor volume reduction correlated with decreased levels of CCL-2, CCL-7, and CCL-12 and increased levels of CXCL-10, CCL-24, CXCL-12, and IL-3." (PMID 38575562, 2024). "Studies have shown that IL-17A can promote ESCC tumor cells to produce more chemokines CCL2, CCL20, and CXCL13, enhance B cell migration, or enhance IgG-mediated antibody and complement-mediated cytotoxicity of B cells to tumor cells to inhibit tumor development." (PMID 39906741, 2024). "Moreover, CCL2 can establish an immunosuppressive microenvironment within tumors, allowing tumor cells to evade immune surveillance and facilitating tumor proliferation." (PMID 39201480, 2024). "Additionally, tumor cells can promote neutrophil infiltration into the perihippocampal meninges via the CCR2‒CCL2 axis, contributing to cognitive decline and anorexia." (PMID 39492832, 2024). "IL-17A/IL-17RA induced CCL2 and attracts macrophages into the tumor environment." (PMID 39906741, 2024). "It has been shown in glioma and breast cancer cell lines that CCL2 expression and receptor engagement can increase proliferation and cancer stem cell self-renewal, suggesting direct roles that may benefit tumor cells in PDAC as well." (PMID 38339310, 2024). "Moreover, we noticed a significant enhancement of CCL2 gene expression in tumor samples on day 3 compared with control." (PMID 35658112, 2024). "CCL2 KD A3250 tumor exhibited higher levels of necrosis and lower levels of tumor proliferation with a striking reduction of F4/80+ macrophage accumulation in the tumor." (PMID 38786066, 2024). "In vitro, Juz- or Gem/Juz-treated KPC tumor cells secreted significantly more macrophage-chemoattractant cytokines, e.g., CCL2, CCL20, and CXCL2, whilst Juz- and Gem/Juz-treated macrophages (MH-S) secreted cytokines of the M1 phenotype, e.g., IL6, TNF-α, and IL12." (PMID 39723364, 2024). "Therefore, CCL2 will likely be crucial in recruiting the CCR2+ monocytic precursors of CD163+ TAMs to tumours, as reported for CCR2+ MDSCs." (PMID 38903497, 2024). "Thus, the concentration of the cytokines CCL2, CCL5, CCL18, and TGFB1 in the CSF was associated with tumor size in patients." (PMID 39272860, 2024). "This study used an orthotopic lymph node metastasis model in mice and found that tumor-associated macrophages (TAMs) infiltrated into lymph node sinuses secreted a large amount of CCL-2 in an autocrine or paracrine manner to induce CCR-2-positive tumor cells metastasize to lymph nodes." (PMID 39328205, 2024). "WNT5A induces CRPC via CCL2 and tumor-infiltrating macrophages." (PMID 38887275, 2024). "Thus, this suggests that CCL2 is critical for NK cell accumulation and plays a more multifaceted role in the anti-tumor response than previously believed." (PMID 38339310, 2024).
tumor (continued). "In addition, we noted that there was a positive correlation between tumor weight and serum CCL2 concentration." (PMID 38970074, 2024). "PRPS2 regulated the chemotaxis of TAM and MDSC in tumor cells by controlling CCL2 expression." (PMID 38952044, 2024). "CCL2-recruited macrophages could promote TAM accumulation in the tumor microenvironment and the production of angiogenic factors, such as VEGF." (PMID 38543085, 2024). "C-C motif chemokine receptor 2 (CCR2), a C-C chemokine receptor, is mainly expressed on immune cells, like the monocytes, macrophages, and T-cells, and can recognize and bind to chemokines, such as CCL2, as well as modulate the migration of immune cells to inflammatory and tumor sites." (PMID 38874512, 2024). "Our own studies with patients after undergoing interstitial HDR brachytherapy of liver metastases correlations were able to show a positive correlation between baseline circulating levels of CCL2 and the tumor volume as well as threshold doses of irradiation damage." (PMID 39199602, 2024). "Also, BDNF, GDNF, NGF, and axon guidance molecules, such as CX3CL1, EphA2, CCL2, Slit, and so forth, are groups of neuroactive chemicals generated by the nerves involved in tumor–nerve interaction." (PMID 39346791, 2024). "Additional research will help clarify whether the BCEV-driven elicitation of robust CCL2 production plays any role in BC recurrence or primary BC tumor progression, with smoking or E-cigarette use potentially exacerbating any emergent oncogenic phenotypes." (PMID 36599909, 2023). "Our data support the notion that the tumor microenvironment, in combination with serum, stimulates CSCs to secrete cytokines, such as IL-6 and CCL2, that act paracrine to cancer cells to enhance their malignant properties, including sphere formation, stem cell characteristics, and migration ability." (PMID 37639070, 2023). "Similarly, in a model of DEN + CCl4-induced fibrosis-HCC, disruption of the CCL2/CCR2 axis reduced tumor burden and pathological vascularization." (PMID 36845555, 2023). "Additionally, N2 inhibits the function of CD8+ T cells, contributes to tumor invasion and metastasis, and promotes tumor progression by recruiting macrophages and Tregs via CCL2 and CCL17." (PMID 37415162, 2023). "Moreover, the endogenous TRAIL signaling pathway can recruit immunosuppressive TAMs by inducing tumor cells to secrete the cytokine CCL2, promoting an immunosuppressive microenvironment and inhibiting cytotoxic T lymphocyte (CTL) activation." (PMID 37605148, 2023). "CCR2 expressing monocytes are recruited along the CCL2 gradient to the peripheral tumor site." (PMID 37849753, 2023). "Thus, HSPCs move to spleen via GM-CSF and CCR2/CCL2 axis and where they are primed to become immunosuppressive MICs to support tumor growth and metastasis via supporting immunosuppressive TIME." (PMID 37380989, 2023). "The tumor volume of control mice was 1.5 times larger than that of anti-mouse CCL2 Ab-treated mice." (PMID 37208442, 2023). "Interestingly, bioinformatic prediction and immunohistochemical/immunofluorescence staining analysis revealed that BCL2A1 expression was obviously associated with the tumor-associated macrophages (TAMs) markers CD68 and CCL2." (PMID 37889551, 2023). "On the other hand, the parental TRAMP-C2 cell line is a selected clone from the TRAMP model, the anti-tumor effect observed in both WT and CCL2 KO MSCs was less likely to be due to immunogenic neo-antigens but rather to the elevated CD45+CD11b+Ly6G− mononuclear population." (PMID 36672395, 2023). "It was found that UVRAG could enhance tumor migration, drug resistance, and CC motif chemokine ligand 2 (CCL2) expression to recruit macrophages by upregulating SP1 expression, resulting in poor prognosis of CRC patients." (PMID 37173968, 2023).